LOXL4 (lysyl oxidase like 4)
Diseases named in the same sentence as LOXL4 in open-access papers (continued):
Sharing a sentence is not in itself a finding about the gene and the disease.
tumor (continued). "We next investigated whether LOXL4 knockdown increased primary tumor growth and metastatic tumor formation in vivo." (PMID 28060764, 2017). "This indicates that increased collagen bundle thickness in LOXL4-knockdown tumors might have accelerated primary tumor growth and lung metastasis in the MDA-MB-231 xenograft model." (PMID 28060764, 2017). "It has also been suggested that LOXL1 and LOXL4 may have tumour-suppressing roles in bladder cancer." (PMID 26804196, 2016). "For example, PIM1 is an ER regulated proto-oncogene that has been shown to play a role in BCa cell proliferation, migration and metastasis and is associated with high grade tumours; KRT13 has been associated with BCa cell growth and metastasis and LOXL4 is an established promoter of cell invasion." (PMID 25488809, 2015). "In addition, targeting LOXL4 promotes growth, survival and migration of this tumor." (PMID 36555458, 2022). "Our prognostic results are parallel to this finding: LOXL4 positivity was associated with improved 2 year disease specific (78.3% vs. 59.6%) and overall (91.3% vs. 72.2%) survival independent of tumor differentiation, but this trend only reached statistical significance for 2 year overall survival." (PMID 33757755, 2022). "This association of a high expression of LOXL4 in neutrophils near vessel co-opting CRCLM in contrast to a lower expression of LOXL4 in neutrophils close to angiogenic CRCLM might emphasize the importance of the interplay between TME and tumor cells." (PMID 33912554, 2021). "However, the role of LOXL4 in tumor biology remains enigmatic." (PMID 30728460, 2019). "The Oxidative Stress pathway activity is drastically affected by a forced reversal of miR-193a-3p or LOXL4 levels in cell and may act at the downstream of LOXL4 gene to relay the miR-193a-3p’s impact on the multi-chemoresistance in both cultured cells and the tumor xenografts in nude mice." (PMID 25311867, 2014). "Mechanistically, exosome-derived LOXL4 orchestrated FAK/Src pathway activation by hydrogen peroxide-mediated signaling, thereby enhancing adhesion, migratory, and invasive potential of tumor cells." (PMID 41567219, 2025). "The results demonstrated a significant decrease in the expression of Ki67 protein in tumor tissues from sh-LOX, sh-LOXL1, sh-LOXL2, sh-LOXL3, and sh-LOXL4 mice, compared to the sh-NC group." (PMID 40270974, 2025). "Flow cytometry analysis revealed a significant reduction in the proportion of M2 macrophages in the tumor tissues of sh-LOX, sh-LOXL1, sh-LOXL2, sh-LOXL3, and sh-LOXL4 groups of mice compared to the sh-NC group." (PMID 40270974, 2025). "The results revealed a predominantly positive correlation between CNA and LOX family members in most tumours, with only a few exceptions noted, such as LOX in LIHC, LOXL1 in TGCT and LOXL4 in HNSC and LGG." (PMID 40179101, 2025). "Immunofluorescent staining revealed increased infiltration and exhaustion of CD8+ T cells in the tumor tissues of mice in the sh-LOX, sh-LOXL1, sh-LOXL2, sh-LOXL3, and sh-LOXL4 groups, compared to the sh-NC group." (PMID 40270974, 2025). "Preliminary observations indicate a decrease in the tumor volume and weight of mice in the sh-LOX, sh-LOXL1, sh-LOXL2, sh-LOXL3, and sh-LOXL4 groups compared to the sh-NC group." (PMID 40270974, 2025). "The results indicated a significant increase in the expression of INF-γ and TNF-α in the tumor tissues of mice from the sh-LOX, sh-LOXL1, sh-LOXL2, sh-LOXL3, and sh-LOXL4 groups compared to the sh-NC group." (PMID 40270974, 2025). "Interestingly, the product of the full length mRNA is found to behave as a tumor suppressor, while the products of the alternatively spliced forms function as promoters of tumor progression, which may explain the contradictory reports concerning the effects of LOXL4 on tumor progression." (PMID 35682926, 2022).
tumor (continued). "Compared with metastatic tumor tissues, the expression of ABCG8 and LOXL4 was higher, whereas that of PDE1B was lower, which was concordant to our findings using the TCGA database." (PMID 33564309, 2021). "The results showed that LOXL1 and LOXL4, particularly LOXL1, were expressed at higher levels in tumor tissues." (PMID 32424143, 2020). "Intriguingly, we found that HCC-derived exosomes transferred LOXL4 proteins between HCC cells, as well as to human umbilical vein endothelial cells (HUVECs), resulting in tumor invasion and metastasis." (PMID 30704479, 2019). "Using global gene expression analysis, we found that a panel of commonly observed hypoxia-inducible genes, including BNIP3L, EGLN3, LOXL4 and P4HA1, were significantly upregulated in the EGFP+ MDA-MB-231 tumor cells, compared to the EGFP− cells." (PMID 29510720, 2018). "Here, we show that pharmacological inhibition of LSD1 inhibits the aggressive features of OSCC by inhibiting key target genes that function in the tumor microenvironment and EMT, including CCN2/CTGF, MMP13, LOXL4 and vimentin." (PMID 29088714, 2017). "Elevated expression of LOXL1, LOXL4 and GUCA1A was detected in tumour cells." (PMID 39286023, 2024). "Clinical analysis reveals a positive correlation between LOXL4 expression in CD68+ cells and PD-L1 levels in human HCC tissue, while high LOXL4 expression in CD68+ cells and low CD8A expression in tumor tissue serve as predictive markers for poor survival in HCC patients." (PMID 37626849, 2023). "T cells stimulated by LOXL4-transfected dendritic cells (DCs) can secrete more IFN-γ, which may enhance the anti-tumor effect." (PMID 36293126, 2022). "Initially, LOXL1 and LOXL4 silencing by methylation were shown to have tumor-suppressive effects in human bladder cancer, while compensation experiments inhibited RAS-mediated ERK activation and reduced tumor-cell colony formation." (PMID 36293126, 2022). "LOXL4 negativity had a hazard ratio of 5.38 (95% CI 1.4–20.7, p = 0.014) for death in Cox regression analysis, independent of tumor stage and differentiation." (PMID 33757755, 2022). "The expression of PLOD1 was upregulated in lysyl oxidase-like 4 (LOXL4) knockout xenograft tumor tissues and LOX4 knockdown could enhance tumor growth and metastasis through collagen-dependent extracellular matrix changes in TNBC." (PMID 31231467, 2019). "The authors of the one other study using LOXL4-knockdown MDA-MB-231 cells concluded that LOXL4 knockdown did not affect primary MDA-MB-231 cell tumor growth, but decreased spontaneous metastasis of MDA-MB-231 cells to the lungs in SCID and non-obese diabetic-SCID mice." (PMID 28060764, 2017). "In addition, there were no noticeable changes in tumor suppression, proliferation, or epithelial-to-mesenchymal transition (EMT), as reflected by Loxl4, periostin, and E-cadherin expression levels." (PMID 31727800, 2019).
cancer (34 papers, 2014 to 2025). A tumor composed of atypical neoplastic, often pleomorphic cells that invade other tissues. "LOXL4 encodes a lysyl oxidase-like protein implicated in collagen remodelling and metastasis formation in cancer." (PMID 29666476, 2018). "In addition, the associations between aberrant LOXL4 expression and its pathophysiological effects in cancer are similar to those observed for other LOX family members." (PMID 28060764, 2017). "Our study unveiled an increased expression of LOX and LOXL1‐3 across various cancer types, whereas LOXL4 expression demonstrated an inverse trend." (PMID 40179101, 2025). "We found that LOXL1 and LOXL4 remarkably enhanced cancer invasiveness among the LOX family genes with altered expression." (PMID 36910659, 2023). "We then extended our approach to an in vivo experiment to investigate the role of LOXL4 in cancer outgrowth in the orthotopic xenograft mouse model." (PMID 37091157, 2023). "Our following study will define the relationship between LOXL4 and the newly identified candidate substrate on the cell surface in cancer outgrowth in vitro and in vivo." (PMID 37091157, 2023). "Previous studies have demonstrated that, contrarily to LOXL2, LOXL4 overexpression has an inhibitory effect on cancer proliferation and progression-related events in different cancer models." (PMID 35800439, 2022). "LOX family members (LOX, LOXL1, LOXL2, LOXL3, LOXL4) reportedly mediate cell migration and metastasis of different cancers." (PMID 34815382, 2021). "For example, LOX, LOXL2, LOXL3, and LOXL4 are overexpressed in more invasive cancers, such as triple negative breast cancers, inducing cancer cell invasion and metastasis." (PMID 32984031, 2020). "So far, scant information is available on the role of LOXL4 in human malignancies, and there are conflicting conclusions regarding the effects of LOXL4 in cancers 28-32." (PMID 32754259, 2020). "We detected the LOXL4 protein levels in these 13 cancer cell lines and found that only KGN cells exhibited moderate LOXL4 protein levels, while the other cell lines had low levels of LOXL4." (PMID 30728460, 2019). "EVs containing lysyl oxidase-like 4 (LOXL4) reprogram stromal cells to support cancer metastasis." (PMID 39857258, 2025). "Next, we asked whether the plasmin production mediated by annexin A2/S100A11 complex on the cell surface of the LOXL4-positive TNBC cells promotes cancer metastasis." (PMID 38595825, 2024). "Moreover, the lysyl oxidase (LOX) family members LOX, LOXL1, and LOXL4 have attracted much attention due to their critical role in cancer metastasis." (PMID 36910659, 2023). "Interestingly, the staining levels of COL1A1, a significant component of cancer-associated collagens, and CD31, a representative endothelial cell marker, were reduced substantially in the LOXL4 KO cell-derived tumors and the LOXL4 mutCA subline-derived tumors." (PMID 37091157, 2023). "We observed that an abundance of LOXL4 induces the multimerized form of annexin A2 via cross-linking, resulting in an inhibition of integrin β-1 internalization, which promotes an integrin β-1-mediated elevation of cancer cell outgrowth." (PMID 37091157, 2023). "Besides annexin A2, we also fortuitously exploited to identify the additional LOXL4 substrate protein on the cancer cell surface, which is conceivable to act to dampen NK cell activation (our unpubl." (PMID 37091157, 2023). "The novel mechanism of LOXL4 that was revealed in the present study may broaden the research concerning LOX-family proteins in cancer biology." (PMID 37091157, 2023). "Bearing in mind this reported event, we hypothesized that LOXL4 prevents this machinery as an adept cancer trait." (PMID 37091157, 2023). "Considering the role of LOXL4 in tumorigenesis, it may serve as a potential independent prognostic marker and therapeutic target for these cancers." (PMID 34393991, 2021). "LOXL4 is increasingly recognized as an important player in cancer progression." (PMID 32754259, 2020).
cancer (continued). "While the role of LOXL1 and LOXL3 in cancer still remains mostly unknown, LOXL4 promotes cell migration and invasion via the FAK (Focal adhesion kinase 1)/Src (Proto-oncogene tyrosin-protein kinase Src) pathway." (PMID 31130685, 2019). "Interestingly, a recent report revealed that, among the LOX family members, LOXL4 mRNA levels alone were higher in cancer tissues from TNBC patients than in those from estrogen receptor-positive breast cancer patients." (PMID 28060764, 2017). "The LOXL4 protein is an important member of the lysyl oxidase (an extracellular copper-dependent amine oxidase) family that catalyzes the first step of the crosslinks between collagens and elastin during the biogenesis of connective tissue and is frequently deregulated in cancer." (PMID 25311867, 2014). "Concerning cancer cell lines, the expression of LOX, LOXL1, LOXL2, LOXL3 and LOXL4 was highest in GBM, GBM, GBM, SKCM and PAAD, while lowest in CLL, CLL, LCML, DLBC and CLL, respectively." (PMID 40179101, 2025). "Genes involved in cancer cell invasion, CTSK and LOXL4, were also upregulated, enhancing our observations on EMT pathway markers." (PMID 40434957, 2025). "In our study, we identified a new role of the LOXL4 secreted in TNBC progression: in addition to its traditional collagen cross-linking function, it also targets cancer cell surface annexin A2 as a substrate for enzymatic cross-linking modification." (PMID 38595825, 2024). "There is limited research on LOXL4, the final member of the LOX protein family to be identified and characterized, in human malignant tumours." (PMID 39247609, 2024). "To clarify the significance of the elevated LOXL4 expression in TNBCs, we established a stable transformant overexpressing wild-type (wt) LOXL4 from MDA-MB-231 cells, and we evaluated its cancer-relevant activities." (PMID 37091157, 2023). "The metastatic potential of cancer can be enhanced by HIF-1α target genes, such as angiopoietin-like 4 (ANGPTL4), lysyl oxidase (LOX), and lysyl oxidase-like 4 (LOXL4)." (PMID 34575983, 2021). "We previously revealed that lysyl oxidase-like 4 (LOXL4) promotes the invasiveness of TNBC cells via cell surface annexin A2 as a novel binding substrate of LOXL4, which promotes the abundant localization of integrin-β1 at the cancer plasma membrane." (PMID 38863623, 2024). "Loxl4-deficient mice have not yet been generated, however, like the other LOX family enzymes, it is also strongly implicated in cancer progression." (PMID 31130685, 2019). "LOXL4 is a secretory lysyl oxidase enzyme and one of the five members of the LOX family of proteins (LOX; LOXL1–4); these proteins enable cross-bridging among extracellular matrices such as collagen and are closely involved in the formation of cancer-growing stroma." (PMID 38595825, 2024).
LOXL4 also shares sentences with these, for which no sentence is quoted: lung carcinoma (4 papers); endometriosis (3); Cirrhosis (2); Infertility (2); laryngeal carcinoma (2); laryngeal squamous cell carcinoma (2); osteosarcoma (2); colon cancer (1); fibrosis (1); fungal infection (1); ischemic stroke (1); kidney carcinoma (1); liver cirrhosis (1); metastatic tumors (1); Obesity (1); oral cancer (1); ovarian serous cystadenocarcinoma (1); prostate carcinoma (1); thyroid cancer (1); viral infection (1).